GJB2 (gap junction protein beta 2)
Diseases named in the same sentence as GJB2 in open-access papers (continued):
Sharing a sentence is not in itself a finding about the gene and the disease.
skin disorder (23 papers, 2011 to 2026). Any deviation from the normal structure or function of the skin or subcutaneous tissue that is manifested by a characteristic set of symptoms and signs. "Pathogenic missense variants in GJB2 are a major cause of nonsyndromic HL and syndromic HL associated with skin disorders." (PMID 37106706, 2023). "Up to now, at least 20 genes of human connexins are known, but skin disorders are only connected with mutations in GJB2 (Cx26), GJB6 (Cx30), GJB3 (Cx31), GJB4 (Cx30.3), and GJA1 (Cx43)." (PMID 25575739, 2015). "Mutations of Gjb2 are associated with sensorineural deafness, skin disorders, peripheral neuropathy and cardiovascular disease." (PMID 23468957, 2013). "In addition, identification of the Asp50Asn mutation in GJB2 allows the accurate classification of the skin disorder in the patient." (PMID 27141831, 2016). "Nevertheless, the lack of skin disorders in GJB2-associated NSHI cases means that the loss or gain of connexin gene function alone may not impact the epidermis development and function as alluded." (PMID 35336849, 2022).
genetic diseases (10 papers, 2015 to 2025). "A GJB2 gene mutation was found in 4.3% (4/92) of patients with simultaneous CI, whereas 15% (6/40) of patients with sequential CI had a genetic disorder such as mutations in GJB2 gene, DFNBA1 gene and LOXHD1 gene." (PMID 41142164, 2025).
infection (7 papers, 2019 to 2025). The state of being infected such as from the introduction of a foreign agent such as serum, vaccine, antigenic substance or organism. "The shRNA-mediated depletion of GJB2 enhanced the spread of HIV-1 over the 18 day infection period in MDDCs, which became more permissible to the virus following pretreatment with virus-like particle (VLP)-Vpx to deplete SAMHD1 protein." (PMID 40980890, 2025). "We found that the GJB2 silencing noticeably enhanced the spread of HIV-1 during the 18 day infection period in MDMs." (PMID 40980890, 2025). "To investigate whether this reduction in GJB2 enhanced infection, we first silenced GJB2 in MDMs using RNA interference in the presence or absence of IL-4 treatment (20 or 50 ng/mL)." (PMID 40980890, 2025).
autosomal recessive disease (3 papers, 2021 to 2025). Autosomal recessive form of disease. "Similar reports have shown GJB2/GJB6 and GJB2/GJB3 variants in 11% of deaf children, and genetic interaction between GJB2 and GJB3 in three unrelated families with autosomal recessive hereditary diseases." (PMID 34276761, 2021).
adenocarcinoma (2 papers, 2014 to 2022). A common cancer characterized by the presence of malignant glandular cells. "The expression of GJB2 was higher in SCC compared to adenocarcinomas (ACC, p < 0.001)." (PMID 35936685, 2022).
bacterial infection (2 papers, 2022 to 2024). "This plot identified GJB2 as the gene that was most robustly upregulated in both bacterial infections." (PMID 39395995, 2024). "Upregulation of GJB2, VNN1, DUSP4, SerpinB7, and IL10, and downregulation of PKMYT1, S100A4, GGTA1P, and SLC22A31 were most strongly associated with bacterial infection." (PMID 39395995, 2024).
peripheral nervous system disease (1 paper, 2023). "A number of these, including connexin 26 (Cx26)/GJB2, Cx29/Cx31.3/GJC3, Cx30/GJB6, Cx32/GJB1, Cx36/GJD2, Cx43/GJA1, Cx45/GJC1 and Cx47/GJC2 are expressed in the central and/or peripheral nervous system and mutations in a number of these cause central and/or peripheral nervous system disease." (PMID 37189458, 2023).
GJB2 also shares sentences with these, for which no sentence is quoted: Hearing impairment (100 papers); lymph node metastasis (7); triple-negative breast carcinoma (7); esophageal squamous cell carcinoma (5); Waardenburg syndrome (5); bladder cancer (4); ectodermal dysplasia (4); skin cancer (4); spinal muscular atrophy (4); Bart-Pumphrey syndrome (3); cardiovascular disease (3); cholestasis (3); hemochromatosis (3); metastatic tumor (3); alopecia (2); Alpha-thalassemia (2); Alzheimer disease (2); bladder neoplasm (2); cardiomyopathies (2); Charcot-Marie-Tooth disease (2); enlarged vestibular aqueduct syndrome (2); Ewing sarcoma (2); familial Mediterranean fever (2); follicular thyroid cancers (2); head and neck squamous cell carcinoma (2); heart failure (2); hemoglobinopathies (2); Joubert syndrome 8 (2); keratoderma (2); Lowe syndrome (2).
A further 174 diseases each share a sentence with GJB2 in 2 papers or fewer.